FGF23 (fibroblast growth factor 23)
Diseases named in the same sentence as FGF23 in open-access papers (continued):
Sharing a sentence is not in itself a finding about the gene and the disease.
Hypertension (continued). "P.gingivalis LPS also promoted the accumulation of unmetabolized renal-specific hormones and enzymes e.g., osteocyte-derived hormone FGF23 in blood and kidney, resulting in hypertension." (PMID 40421989, 2025). "For instance, higher FGF23 levels are positively correlated with hypertension and increased systolic blood pressures in community-dwelling older adults [1041]." (PMID 40407975, 2025). "Participants with higher hsCRP quartiles were more likely to have had a history of stroke, HF, microalbuminuria/macroalbuminuria, and hypertension with higher FGF-23 and NT-proBNP (each P < 0.05)." (PMID 41151250, 2025). "Further comprehension of the interplay among hypertension, aldosterone, and inflammation, considering potential undiscovered aspects of FGF-23 biology, is warranted." (PMID 39989455, 2025). "Angiotensin II can regulate the bone expression of FGF23, thereby increasing its circulating levels with an added effect on hypertension." (PMID 41426862, 2025). "Clinical studies have shown an independent correlation between elevated circulating FGF23 levels and increased cardiovascular risks, including hypertension, atherosclerosis, and stroke [1041–1043]." (PMID 40407975, 2025). "LVH developed independently of cardiac FGF23, but cardiomyocyte-specific Fgf23 knock-out (Fgf23CKO) TAC mice were characterized by ameliorated hypertension and a distinct reduction of cardiac fibrosis, relative to Fgf23fl/fl TAC controls." (PMID 41152461, 2025). "This study examined the involvement of fibroblast growth factor-23 (FGF-23) in primary aldosteronism (PA), a condition characterized by elevated aldosterone levels and hypertension." (PMID 39989455, 2025). "Our findings revealed significant associations between higher FGF23 levels and MBD, lower eGFR, more advanced CKD progression (particularly those requiring KRT), hypertension, and greater LVMI." (PMID 39433982, 2024). "In multivariate analysis, CKD stages, hypertension stages, the presence of MBD, and LVMI were associated with FGF23 levels (p < 0.05)." (PMID 39433982, 2024). "In this population, we observed that patients with higher pre-KT FGF23 levels were more likely to have post-transplant hypertension." (PMID 40115543, 2024). "Serum fibroblast growth factor-23 levels are similar between pregnancies complicated with gestational hypertensive disease and normotensive pregnancies." (PMID 39045952, 2024). "Considering the characteristics of the population with and without MALE during follow-up, we observed differences in male sex, hypertension, and Klotho and FGF23 baseline levels." (PMID 37061530, 2023). "Given that aging, hypertension, and metabolic syndrome are major causes of CKD, FGF-23 appears to have important clinical implications for assessing the risk of RKFD in healthy subjects." (PMID 36671416, 2022). "The upregulation of FGF-23 contributes to vascular calcium deposition and sodium reabsorption in sodium chloride cotransporter, resulting in blood volume expansion and hypertension." (PMID 36364791, 2022). "Second, the associations between both baseline urinary potassium excretion and FGF23 and incident hypertension were assessed." (PMID 34960084, 2021). "It indicated that a high-phosphorus diet can induce the occurrence of hypertension and lead to an increase in FGF23." (PMID 34861810, 2021). "High plasma fibroblast growth factor 23 (FGF23) and low potassium intake have each been associated with incident hypertension." (PMID 34960084, 2021). "Diabetic nephropathy leads to a compensatory increase in blood FGF23 levels and the renal accumulation of unmetabolized FGF23, resulting in hypertension and cardiovascular diseases." (PMID 33407253, 2021). "Current results extend a prior analysis in the PREVEND cohort on the relationship between potassium excretion and incident hypertension by specifically addressing potential mediation by FGF23." (PMID 34960084, 2021).
Hypertension (continued). "In conclusion, kidney dysfunction in the background of arterial hypertension and alterations of FGF23/α-Klotho axis has a substantial impact on cardiomyocyte hypertrophy and interstitial fibrosis." (PMID 33924991, 2021). "Despite the induction of pathological cardiac remodeling due to increased FGF23 in CKD, the relationship between high FGF23 levels and the development of hypertension is unclear." (PMID 34536161, 2021). "The exact relationship between increased FGF23 and post-transplant hypertension remains poorly understood." (PMID 32613001, 2020). "Peripheral neuropathy and hypertension were more prevalent in patients with FGF-23 above the median." (PMID 32998751, 2020). "The pathophysiology of the cardiac consequences of CKD involves multiple factors, including hypertension, uremic toxins, FGF-23, and activation of the renin angiotensin aldosterone system." (PMID 32001792, 2020). "VDD+AmB/LE rats also presented alterations in the PTH-Klotho-FGF-23 signaling axis, urinary concentrating defect and hypertension, probably due to an inappropriate activation of the renin-angiotensin-aldosterone system." (PMID 31295336, 2019). "Overall, 27% of the participants developed a hypertension, whereby the prevalence increased independently of kidney function in the highest decile of serum FGF23." (PMID 31698866, 2019). "Through stimulation of NCC expression, FGF23 increases renal Na+ retention, which consequently triggers plasma volume expansion and, consequently, hypertension." (PMID 31698866, 2019). "In conclusion, we did not observe a significant effect of vitamin D3 supplementation on FGF23 concentrations in patients with vitamin D insufficiency and arterial hypertension." (PMID 29602956, 2019). "Apart from that, FGF23 plays a key role in controlling serum phosphate levels to attenuate phosphate-induced VC and hypertension." (PMID 31698866, 2019). "For example, FGF-23 upregulates NCC in the DT leading to hypertension and suppression of aldosterone levels." (PMID 29946298, 2018). "Our study found that FGF23 played an important role in the pathogenesis of hypertension in young population." (PMID 26321027, 2015). "In multivariate analyses, FGF-23 plasma levels and calcidiol categories remained as independent predictors of outcome, along with age and hypertension." (PMID 24748388, 2014). "Moreover, based on our data, it is conceivable that high dietary phosphate intake might predispose to the development of CKD and hypertension through augmented FGF23-induced SGK1 activation and Na+ retention also in the normal population and that aldosterone might modulate this effect." (PMID 24797667, 2014). "Experimental studies have shown that excess Pi consumption, largely from inorganic Pi used as a preservative or flavor enhancer in processed foods, and increased FGF23 may contribute to vascular abnormalities, thereby promoting hypertension." (PMID 41683565, 2026). "Initially, the limited number of studies on hypertension, serum magnesium, FGF-23, and ALP in the included literature may be attributed to language barriers, leading to an inadequate sample size." (PMID 40314886, 2025). "In addition, a rat model of CKD type 4 CRS induced by 5/6 nephrectomy, these animals develop elevated FGF23, hypertension, and LVH." (PMID 41300756, 2025). "However, the correlation between hypertension, serum magnesium, fibroblast growth factor-23 (FGF-23), alkaline phosphatase (ALP), and MHD with concomitant CAC was not significant, likely due to the wide variation in sample size and study type." (PMID 40314886, 2025). "Excess FGF23, in the context of low Klotho, can exert off-target effects, including direct stimulation of sodium reabsorption in the distal tubule, promoting volume expansion and hypertension." (PMID 41303567, 2025). "Previous studies have demonstrated a relationship between FGF23 levels and hypertension." (PMID 40115543, 2024).
Hypertension (continued). "In this cross-sectional study, we did not confirm an increase in FGF23 levels in the study population and its association with reduced eGFR, hypertension, or abnormal ejection fraction in echocardiography." (PMID 38792509, 2024). "So far it is known that the promotion of LVH by FGF23 could be induced via a direct activation of Fibroblast growth factor receptor 4 on cardiac myocytes as well as through FGF23 induced volume expansion and hypertension." (PMID 35559350, 2022). "In our current study, we observed that treadmill exercise training could also decrease protein levels of AT1R and FGF-23 for the early aged hypertension." (PMID 35604403, 2022). "FGF23 may contribute to RAAS activation, and promote renal sodium reabsorption driving the risk of hypertension." (PMID 34960084, 2021). "Based on the augmented renal functional impairment, increased circulating FGF23, increased renal fibrosis, and the presence of hypertension in 5/6-Nx mice on CPD compared with 5/6-Nx mice on ND, we decided to perform all subsequent experiments in mice maintained on CPD." (PMID 34290280, 2021). "FGF23 did not mediate the association between urinary potassium excretion and incident hypertension." (PMID 34960084, 2021). "However, these animals develop hypertension suggesting that enhanced expression of FGF23 itself is sufficient to disrupt blood pressure regulation and evoke disease independent of RAAS." (PMID 34050126, 2021). "No potential mediation effect by FGF23 was found, as the point estimate of the HR of the association of urinary potassium excretion with incident hypertension did not change after adjustment for FGF23 (model 3)." (PMID 34960084, 2021). "Since, hypertension is one of the most common comorbidities in CKD patients, FGF23-mediated activation of RAAS may play an important role in hypertension in CKD." (PMID 34422725, 2021). "Additionally, we investigated for the first-time cell type-specific regulation of FGF23 in heart tissue due to high blood pressure showing increased synthesis in cardiac fibroblasts and endothelial cells." (PMID 35118076, 2021). "It was later hypothesized that FGF23 induced the activation of FGFR1, leading to Ace2 reduction, causing hypertension." (PMID 32982979, 2020). "Therefore, FGF23 is thought to contribute to the development of hypertension by modulating the renin–angiotensin–aldosterone system (RAAS)." (PMID 31698866, 2019). "Altogether, the clinical and experimental data emphasize that high phosphate and FGF23 levels may contribute to hypertension not only in CKD patients, but also in the general population." (PMID 31698866, 2019). "This is at least partly because of high FGF23 and phosphate levels, as several clinical studies showed an association between increased serum FGF23 or phosphate and the presence of hypertension in CKD patients, as well as in non-CKD populations." (PMID 31698866, 2019). "Possible indirect mechanisms such as the phosphate-mediated elevation of FGF23 or development of hypertension may contribute to the development of LVH in CKD patients." (PMID 31698866, 2019). "The ARIC (Atherosclerosis Risk in Communities) study evaluated the correlation of serum intact FGF23 levels and the development of hypertension in a large cohort of 7948 middle-aged (45–64 years) participants without previous hypertension during a median follow-up of 5.9 years." (PMID 31698866, 2019). "Indeed, upregulation of FGF23 was reported in patients with hypertension, advanced diabetic nephropathy, and cardiovascular disease or in patients with end stage liver disease." (PMID 29907141, 2018). "This study found that FGF23 may play an important role in the pathogenesis of hypertension in children and adolescents, but our results should be confirmed by further studies." (PMID 26321027, 2015).
Hypertension (continued). "This review highlights current evidence linking Pi-induced FGF23 pathogenically to hypertension, with focus on FGF23 translocation to and FGFR4 signaling in the central nervous system as a potential mechanism and therapeutic target for hypertension associated with high Pi intake and CKD." (PMID 41683565, 2026). "Furthermore, there is evidence of the influence of FGF23 on renal sodium reabsorption and its effect on vessels and cardiomyocytes, which could potentially contribute to the presence of hypertension and left ventricular hypertrophy in this population." (PMID 38542517, 2024). "It indicates that FGF23 may indirectly affect the development of hypertension." (PMID 38139126, 2023). "Therefore, low FGF23 serum levels and low sodium chloride intake may have a protective effect for hypertension in some species." (PMID 36428422, 2022). "The pathophysiological mechanisms underlying hypertension in Hyp mice are not entirely clear, but they may be related to an FGF23-mediated upregulation in renal sodium-chloride cotransporter (NCC) abundance." (PMID 35884995, 2022). "However, adding FGF23 to the multivariable model did not change the point estimate of the hazard ratio of the association between urinary potassium and incident hypertension." (PMID 34960084, 2021). "However, no mediation effect of FGF23 was found between the inverse association of urinary potassium excretion and incident hypertension." (PMID 34960084, 2021). "From a teleological perspective, FGF-23 control of blood pressure may serve to attenuate the hypotensive effects of inflammation, or alternatively account for the link between inflammation and hypertension." (PMID 29946298, 2018). "Moreover, the observation that elevations of FGF-23 exacerbate the severity of Ang II-induced hypertension and LVH in the Hyp mouse model, indicates that FGF-23 and RAAS may work through complementary pathways to enhance cardiovascular responses." (PMID 30120363, 2018). "Contributors to LVH, aside from hypertension in individuals with CKD, include CKD mineral and bone disorder (e.g., fibroblast growth factor 23, hyperparathyroidism), anemia, uremic toxins, and inflammation." (PMID 41053527, 2025). "We recruited patients with unilateral PA (uPA) and observed increased levels of C-terminal FGF-23 (cFGF-23) and C-terminal to intact FGF-23 (iFGF-23) in patients with uPA compared with essential hypertension control participants." (PMID 39989455, 2025). "Kruskal-Wallis analysis showed that FGF23 was significantly correlated with CKD stage (p < 0.01) and hypertension (p < 0.02)." (PMID 39433982, 2024). "The two MHD groups had a higher prevalence of hypertension, blood creatinine, BUN, PTH, blood phosphorus, FGF23, and D-serine than the control group, but also lower Hb, RBC, and ALB (all P < 0.01)." (PMID 36649363, 2023). "GDF-15 (p < 0.001), Troponin-T (p = 0.002), FGF-23 (p = 0.006), and IGFBP-7 (p = 0.018) abundance was higher in patients with hypertension." (PMID 35859587, 2022). "Reports of cardiovascular abnormalities and hypertension in patients with XLH are rare, inconsistent, and considered to be side effects of conventional therapy and/or FGF23-driven increased renal sodium reabsorption." (PMID 30808384, 2019). "Elevations of FGF-23 are purported to contribute to adverse cardiovascular effects as evidence by the finding of hypertension and LVH in the Hyp mouse model of FGF-23 excess." (PMID 30120363, 2018). "With increasing quartile of FGF23 eGFR decreased, PTH increased and prevalence's of CVD and hypertension increased." (PMID 23587028, 2013). "Plasma levels of cFGF-23 (AUC = 0.844), iFGF-23 (AUC = 0.767), c/i FGF-23 ratio (AUC = 0.724), and PAC (AUC = 0.617) at the time of PA confirmation were predictive of hypertension remission following adrenalectomy, with cFGF-23 level demonstrating superior predictive ability." (PMID 39989455, 2025).
Hypertension (continued). "Median FGF23 was not significantly different between subjects with or without hypertension in both the T1D and control group." (PMID 38124483, 2024). "Anemia, hypertension, MBD, and malnutrition were prevalent among the study population, and higher FGF23 levels correlated with CKD severity and cardiovascular parameters, such as hypertension and LVMI, consistent with our hypothesis." (PMID 39433982, 2024). "Further multivariate regression analysis showed that LVMI, CKD stages, hypertension stages, and the presence of MBD were associated with FGF23 levels and no variables were found to be associated with cIMT." (PMID 39433982, 2024). "The association between high FGF-23 levels and a higher risk of RKFD was more significant in patients with younger age and cardiovascular disease and those without hypertension, metabolic syndrome, or gout." (PMID 36671416, 2022). "On the other hand, in subgroup analysis, we found that the trend of the association between a high FGF-23 level and RKFD was more significant in the younger subjects and those without hypertension or metabolic syndrome." (PMID 36671416, 2022). "In conclusion, our results confirm that vitamin D deficiency induces AmB/LE nephrotoxicity possibly due to impaired renal function accompanied by tubular injury, the arising of hypertension, alterations in the PTH-Klotho-FGF-23 signaling axis and water balance dysfunction." (PMID 31295336, 2019). "Comparatively, patients with T2D and hypertension had significantly higher creatinine and FGF23 values as compared to those patients with CKD but without said comorbidities." (PMID 29665793, 2018). "Hypertension was not related to FGF23 and therefore cannot explain the rise in proteinuria with increasing FGF23 levels." (PMID 22530966, 2012). "Mice with X-linked hypophosphatemic rickets (XLH) characterized by high FGF23 levels do not show hypertension, suggesting that FGF23 may not affect blood pressure directly." (PMID 35966090, 2022). "FGF23 may instead contribute to cardiovascular disease in CKD by directly interacting with FGFR4 on cardiomyocytes to induce cardiomyocyte hypertrophy or with hepatocyte FGFRs to induce hypertension which can lead to blood vessel calcification." (PMID 30808384, 2019). "The investigation of the effect of FGF23 on hypertension is not confined to in vitro models." (PMID 26321027, 2015). "The hypothesis that increased cIMT is influenced by abnormal BMI, hypertension, advanced CKD, presence of MBD, high FGF23, and high LVMI was not confirmed in this study." (PMID 39433982, 2024).